TTN (titin)
Description:
Key component in the assembly and functioning of vertebrate striated muscles. By providing connections at the level of individual microfilaments, it contributes to the fine balance of forces between the two halves of the sarcomere. The size and extensibility of the cross-links are the main determinants of sarcomere extensibility properties of muscle. In non-muscle cells, seems to play a role in chromosome condensation and chromosome segregation during mitosis. Might link the lamina network to chromatin or nuclear actin, or both during interphase.
Synonyms: CMPD4; FLJ32040; TMD; CMH9; LGMD2J; MYLK5; CMD1G; CMYO5; CMYP5; EOMFC; HMERF; LGMDR10; SALMY
Tractability: Small molecule: a structure with a bound ligand is known; it belongs to a druggable protein family. Antibody: its Gene Ontology location is reachable by antibodies, with high confidence. PROTAC: ubiquitination databases record sites on it; its protein half-life has been measured.
Target class: Enzyme; Transferase
Gene: Protein-coding gene on chromosome 2 (178,525,989 to 178,830,802, reverse strand). Ensembl gene ENSG00000155657.
Subcellular location: Cytoplasm; Nucleus
Pathways (Reactome):
Hemostasis: Platelet degranulation
Muscle contraction: Striated Muscle Contraction
Gene Ontology:
Molecular function: actin filament binding; actinin binding; calcium ion binding; calmodulin binding; enzyme binding; identical protein binding; muscle alpha-actinin binding; protease binding; protein binding; protein homodimerization activity; protein kinase binding; protein kinase regulator activity; protein serine/threonine kinase activity; protein tyrosine kinase activity; structural constituent of muscle; structural molecule activity conferring elasticity; telethonin binding; ATP binding; cytoskeletal protein binding; protein kinase activity; protein serine kinase activity; structural molecule activity
Biological process: cardiac muscle cell development; cardiac muscle contraction; cardiac muscle hypertrophy; cardiac muscle tissue morphogenesis; cardiac myofibril assembly; detection of muscle stretch; mitotic chromosome condensation; positive regulation of cAMP/PKA signal transduction; positive regulation of gene expression; response to calcium ion; sarcomere organization; sarcomerogenesis; skeletal muscle myosin thick filament assembly; skeletal muscle thin filament assembly; muscle contraction; muscle filament sliding; skeletal muscle contraction; striated muscle contraction
Cellular component: condensed nuclear chromosome; extracellular exosome; I band; titin-telethonin complex; Z disc; cytosol; extracellular region; M band; actin cytoskeleton; cytoplasm; nucleus
Genetic constraint (gnomAD): Loss-of-function variants: 1,461 observed, 3,183.5 expected, observed/expected ratio (o/e) 0.46, 90% interval 0.44 to 0.48. The upper end of that interval is the gene's LOEUF score, 0.48, which puts it in group 2 of 6, group 1 being the genes least tolerant of losing a copy. Missense variants: 40,245 observed, 44,309 expected, observed/expected ratio (o/e) 0.91, 90% interval 0.9 to 0.92. Synonymous variants: 13,927 observed, 15,528 expected, observed/expected ratio (o/e) 0.9, 90% interval 0.88 to 0.91.
Gene-disease validity (ClinGen):
ClinGen rates the evidence that TTN causes each of these diseases.
dilated cardiomyopathy 1G (autosomal dominant): Definitive.
myopathy, myofibrillar, 9, with early respiratory failure (autosomal dominant): Definitive.
TTN-related myopathy (autosomal recessive): Definitive. A disorder of the musculoskeletal system caused by pathogenic variants in the TTN gene encoding the titin protein expressed in striated muscle.
tibial muscular dystrophy (autosomal dominant): Moderate. A distal myopathy characterized by weakness of the muscles of the anterior compartment of lower limbs, appearing in the fourth to seventh decade of life.
hypertrophic cardiomyopathy (autosomal dominant): Limited. A condition in which the myocardium is hypertrophied without an obvious cause.
arrhythmogenic right ventricular cardiomyopathy (autosomal dominant): Disputed.
Homologues: Orthologues: macaque TTN (96% identical), chimpanzee TTN (95% identical), mouse Ttn (89% identical), rat Ttn (86% identical), dog TTN (71% identical), zebrafish ttn.2 (45% identical).
Diseases named in the same sentence as TTN in open-access papers:
TTN is named in the same sentence as 352 diseases in open-access papers, as found by Europe PMC text mining. Sharing a sentence is not in itself a finding about the gene and the disease. The quoted sentences say what the papers report.
cardiomyopathy (183 papers, 2007 to 2026). A disease of the heart muscle or myocardium proper. "Background/Objectives: Titin (TTN; OMIM 188840) is the largest known human sarcomeric protein, and pathogenic variants in the TTN gene cause a broad spectrum of inherited myopathies and cardiomyopathies." (PMID 42123284, 2026). "Although primarily linked to cardiomyopathies, TTN mutations frequently appear in lung adenocarcinoma, CRC, and melanoma." (PMID 40422048, 2025). "TTN variants are associated with myopathies, muscular dystrophies, and cardiomyopathies (OMIM 188840), which are inconsistent with the phenotypes of these probands, and COL24A1 variants have not been associated with Mendelian phenotypes." (PMID 40662098, 2025). "Heterozygous truncation variants in the gene TTN encoding titin are the leading cause of genetically mediated cardiomyopathy, accounting for up to 25% of familial DCM cases and 18% of sporadic cases." (PMID 39959973, 2025). "Another patient whose MYH7 variant was initially classified as VUS also had a rare nonsynonymous variant in RNA binding motif protein 20 (RBM20 p.Ile921Val), a titin-splicing gene implicated in cardiomyopathy." (PMID 40791945, 2025). "We observed significant associations with individual cardiomyopathy genes, finding that mitral annular plane systolic excursion associated with TTN and TNNT2, and LA pump volume and RA-EF associated with MYH7." (PMID 40660250, 2025). "While the role of truncation mutations of TTN in cardiomyopathy is accepted, it is likely the mutant allele would produce alterations in titin isoform composition or expression level with abnormal properties that contributes to HF." (PMID 41144497, 2025). "Our data demonstrate that inhibition of HDAC5 effectively reverses TTN-silencing-induced gene dysregulation, thereby identifying HDAC5 as a promising therapeutic target in TTN-deficient related cardiomyopathy." (PMID 41283336, 2025). "Some notable examples include combinations of DMD variants with titin (TTN) truncating variants, which typically present with early-onset muscle weakness and severe cardiomyopathy." (PMID 40134720, 2025). "Beyond DCM, TTN variants have also been implicated in other cardiomyopathies such as HCM, peripartum cardiomyopathy (PPCM), and arrhythmogenic right ventricular cardiomyopathy (ARVC)." (PMID 41283336, 2025). "Genotype–phenotype correlations in TTN-related cardiomyopathies reveal that mutations in different titin regions distinctly impact disease penetrance, severity, and outcomes." (PMID 41190030, 2025). "The ongoing inquiry into the exact molecular mechanisms by which TTN mutations lead to cardiomyopathies illuminates the intricate relationship between TTN mutations and various forms of cardiomyopathies." (PMID 38438525, 2024). "There is an increased prevalence of rare variants (BAG3, LMNA, MYH7, TCAP, TNNT2, and TTN), particularly TTNtv, in adult and pediatric cancer patients with cancer therapy-induced cardiomyopathy." (PMID 39070560, 2024). "Titin, encoded by the gene TTN, is involved in specific types of muscular dystrophy and cardiomyopathy." (PMID 38434421, 2024). "Disruptions in these findings, due to mutations in genes like MYL4 and TTN, lead to cardiomyopathies and structural defects." (PMID 39202774, 2024). "The patient's nonischemic dilated cardiomyopathy (DCM) highlights the critical role of genetic factors, particularly titin gene (TTN) mutations, in cardiomyopathy pathogenesis." (PMID 38868113, 2024). "Truncating variants in the TTN gene (TTNtvs) have been implicated in numerous cardiomyopathies, including DCM and other environment-influenced cardiomyopathies such as peripartum, alcohol-induced, and chemotherapy-induced, cardiomyopathy." (PMID 38771459, 2024). "Myopathies can be associated to cardiac phenotypes, and some genes are implicated in both myopathy and cardiomyopathy, such as TTN and SPEG." (PMID 39625536, 2024).
cardiomyopathy (continued). "A disruption in these results, for example, by mutations in MYH7 and TTN, results in cardiomyopathies." (PMID 39202774, 2024). "This narrative review aimed to comprehensively summarize current evidence on TTN variants identified in published cardiomyopathy studies and determine which specific variants are likely pathogenic contributors to cardiomyopathy development." (PMID 38438525, 2024). "First, we show the utility of CASAAV-HDR for disease modeling applications by using CASAAV-HDR to create and precisely tag two pathological variants of the titin gene observed in cardiomyopathy patients." (PMID 39677651, 2024). "Mutations in the TTN gene, particularly truncating variants (TTNtv), are associated with various cardiomyopathies, most notably dilated cardiomyopathy." (PMID 39359474, 2024). "The goal of this review is to discuss the current state of understanding regarding the challenges in establishing clear associations between particular TTN mutations and specific cardiomyopathy subtypes in a clinical context." (PMID 38438525, 2024). "We identified variants in a cardiomyopathy-associated gene (TTN) suggesting a role for sarcomere homoeostasis as a mediator of human cardiac ageing." (PMID 37604819, 2023). "Previous research showed that TTN gene variants were associated with various cardiomyopathies and a range of skeletal muscle diseases." (PMID 36721086, 2023). "TTN/CCDC141 rs10497525 is an intron variant of the large sarcomeric protein, titin; variations on this gene cause muscle disorders and cardiomyopathies." (PMID 37372394, 2023). "Correction of truncated titin proteins using CRISPR/CAS technique results in functional recovery and appears to be a promising therapeutic target for the treatment of titin mutation-based cardiomyopathy." (PMID 35846001, 2022). "It is noteworthy that the TTN gene encodes titin, which has been reported to associate with muscular and cardiomyopathy diseases, implying a potential relationship between TTN and MFS." (PMID 35207686, 2022). "After a survey of 76 target genes, an in-frame deletion of the titin gene was recognized as the most possible genetic defect responsible for his cardiomyopathy caused by anthracycline." (PMID 36012532, 2022). "TTN mutations are associated with neuromuscular disease, cardiomyopathy, and the development of solid tumors." (PMID 35733807, 2022). "Rare genetic alterations in the TTN gene are associated with inherited cardiomyopathies, mainly DCM." (PMID 35207729, 2022). "Previously observed mutations of the TTN gene are mostly related to cardiomyopathy and skeletal muscle diseases." (PMID 35979353, 2022). "The genes showing heterozygous variants inherited from the healthy father and related to AD diseases are TTN, related to AD myopathies and cardiomyopathies and MET, related to AD susceptibility to Osteofibrous Dysplasia (OMIM #607278)." (PMID 35368691, 2022). "While none of these specific variants have been described as pathogenic, PRDM16, SYNM and TTN are well-known cardiomyopathy-associated genes." (PMID 35260914, 2022). "That is why, mutations of TTN can result in isolated cardiomyopathies, isolated skeletal muscle disorders, and combined cardiac-skeletal muscle diseases." (PMID 35951140, 2022). "Most commonly, the culprit mutations that serve as a first hit are related to known cardiomyopathy genes, again the TTN gene in particular." (PMID 35498019, 2022). "Consistently, genetic variants in cardiomyopathy-causative genes, such as truncation variants in the titin gene, significantly increased the risk of anthracycline drug-associated cardiomyopathy and adverse cardiac events." (PMID 34327238, 2021). "Titin truncating variants are a well-established cause of cardiomyopathy; however, the role of titin missense variants is less well understood." (PMID 33637999, 2021).
cardiomyopathy (continued). "The entire TTN gene consists of 364 exons, located on chromosome 2q31, and its mutation is thought to be related to a variety of skeletal muscle and cardiomyopathy." (PMID 34635074, 2021). "Mutations in titin and MyBP-C are well-established inducers of different forms of human cardiomyopathy." (PMID 34466164, 2021). "Other forms of cardiomyopathies, such as hypertrophic cardiomyopathy and arrhythmogenic right ventricular cardiomyopathy are also linked to TTN mutations." (PMID 34154667, 2021). "Protein-altering mutations in TTN have been identified in patients with cardiomyopathy and women with preeclampsia are more likely to carry TTN mutations associated with idiopathic cardiomyopathy and peripartum cardiomyopathy." (PMID 35719905, 2021). "TTN is the gene encoding titin which is the largest protein of the human genome having 305 kbs and is involved in cardiomyopathies." (PMID 34722422, 2021). "Specifically, arrhythmogenic-cardiomyopathy-causing mutation T16I was found to decrease the mechanical stability of the Ig10 domain of titin, although this effect is concomitant with a marked decrease in thermodynamic stability." (PMID 34466164, 2021). "TTN missense variants are detected in both cardiomyopathy cases and controls, hence it is assumed that the large majority do not cause disease." (PMID 33637999, 2021). "In this study, we have generated a novel mouse model for the TTN missense variant A178D, which was originally identified as the most likely cause of cardiomyopathy in a family affected by both DCM and LVNC." (PMID 33637999, 2021). "Taken together, this is a robust indication that the titin A178D missense variant is solely responsible for the DCM aspect of cardiomyopathy in the reported family." (PMID 33637999, 2021). "It is known from the literature that truncating TTN mutations lead to a late onset cardiomyopathy in 95% of the cases." (PMID 34201072, 2021). "Second, several cardiomyopathy-associated proteins, such as γ-catenin, titin, small muscular protein, and myomesin, have been identified in the phosphoproteomics data." (PMID 34966794, 2021). "Approximately 20% of PPCM patients screened for cardiomyopathy genes have an identified pathogenic mutation, with TTN truncations most commonly implicated." (PMID 33467574, 2021). "A cardiomyopathy panel identified a TTN truncating A‐band variant (c.76717C>T; p.Arg25573*), interpreted as likely pathogenic." (PMID 32815318, 2020). "Whole-exome sequencing revealed a high incidence of mutations in genes associated with either cardiomyopathies, including Titin variants, and/or the DNA damage response/repair system (DDR) in PPCM patients with a history of cancer." (PMID 32542459, 2020). "These recent studies demonstrate that titin mutations have significant organism-wide effects on phenotype beyond those traditionally considered in myopathy and cardiomyopathy." (PMID 32492876, 2020). "Most prominent are genetic variants associated with dilated cardiomyopathy, especially Titin truncating variants that increase the risk of cancer therapy-induced cardiomyopathies." (PMID 32542459, 2020). "Transcriptional modifications of titin are associated with both systolic and diastolic dysfunction and therefore titin represents a viable therapeutic target for treatment of cardiomyopathy." (PMID 32859027, 2020). "Currently, cardiomyopathy is associated with heterozygous A‐band TTN variants, whereas skeletal myopathy is largely associated with homozygous or compound heterozygous TTN variants." (PMID 32815318, 2020). "In 8/12 probands (66.7%), we found likely causative variants in known cardiomyopathy genes (TTN, DSP, SCN5A, TNNC1, TPM1, CRYAB, and MYH7), which were confirmed as de novo (six DCM, one HCM, and one RCM case)." (PMID 32013205, 2020). "Despite the relatively large effects of these mutations on the expressed titin protein, many titin mutations are associated with relatively late onset myopathy and/or cardiomyopathy." (PMID 32492876, 2020).